EGFR (epidermal growth factor receptor)
Diseases named in the same sentence as EGFR in open-access papers (continued):
Sharing a sentence is not in itself a finding about the gene and the disease.
lung cancer (continued). "Therefore, with overexpression of PAR2 in NSCLC cells, PAR2 blockade sensitized gefitinib to attenuate EGFR activation and lung cancer cell viability." (PMID 33967759, 2021). "The latest study revealed that p62 expression might target PD-L1, and p62 signaling axis could be useful to suppress the EGFR-TKI-resistant lung cancer." (PMID 34094898, 2021). "A549 with wild-type EGFR was most sensitive to cinobufagin among these selected lung cancer cells." (PMID 34925034, 2021). "Here, we hypothesized that PHLPP is a key regulator of EGFR-TKI sensitivity and a potential treatment target for overcoming resistance to EGFR-TKI in lung cancer." (PMID 34168988, 2021). "In addition to switching to SCLC-like, transition of LUAD cells to squamous cell carcinoma (SCC) accounts for a small fraction of EGFR mutant lung cancer patients leading to EGFR TKI resistance." (PMID 34298815, 2021). "In addition, in lung cancer, the presence of the EGFR protein in exosomes from patient plasma has been suggested to represent a biomarker for lung cancer diagnosis." (PMID 34283059, 2021). "Although there is no direct association between Postn and EGFR in lung cancer, Postn can regulate EGFR interacting partners or its downstream signaling." (PMID 34976811, 2021). "EGFR-targeted treatment is widely used in the clinic for patients with lung cancer." (PMID 33391435, 2021). "Furthermore, miR-214 knockdown saw previously resistant EGFR-mutant lung cancer cells now sensitive to gefitinib, as shown in MTS viability assays." (PMID 34943783, 2021). "EGFR-targeting by erlotinib did correlate with EGFR mutation status in most, but not all, lung cancer organoids." (PMID 33816288, 2021). "This has been confirmed particularly in patients with lung cancer, in which high expression levels of CDKN1A with wild-type EGFR status was associated with better survival, whereas CDKN1A expression with oncogenic EGFR mutations was correlated with poor outcome." (PMID 33430083, 2021). "As a result of these advances, EGFR-mutant lung cancer patients are living longer than ever before." (PMID 34572868, 2021). "However, there is limited evidence suggesting the use of TKI in EGFR-mutant lung cancer patients who suffer from respiratory failure and need ICU admission." (PMID 34680533, 2021). "Patients with advanced lung cancer, SMPM, lung cancer first, combined with tumor only receiving palliative treatment and without EGFR gene mutation had a poor prognosis." (PMID 33478184, 2021). "The distribution of TMB had not been fully characterized in Chinese lung cancer patients with no EGFR or ALK mutations." (PMID 33643802, 2021). "Expression of Gene 33 in lung cancer cells can also be affected by the level of EGFR." (PMID 34206547, 2021). "Accumulating evidence indicates a correlation between fibrinogen and EGFR in lung cancer." (PMID 34976811, 2021). "BRAFV600E mutations have been identified as a resistance mechanism to osimertinib in roughly 3% of cases with EGFR-mutant lung cancer, with or without concurrent EGFRT790M mutation." (PMID 34921211, 2021). "Oncogenes in the EGFR/RAS pathway display ‘oncogene addiction’, a tumor-specific reliance on sustained cell signaling for cell survival, and consequently these mutated oncogenes represent powerful drug targets for lung cancer therapy." (PMID 34373451, 2021). "The EGFR signaling pathway plays an important role in multiple lung cancers." (PMID 34200786, 2021). "ALK rearrangements were shown to be associated with increased VTE risks in patients diagnosed with non-small lung cancer, while there was no significant relation observed between VTE risks and EGFR or KRAS mutations in lung cancer patients." (PMID 33996610, 2021).
lung cancer (continued). "We identified the clinicopathological features and DDR mutation spectrum of 122 advanced lung cancer samples without EGFR or ALK mutations/translocations." (PMID 34604048, 2021). "The membrane of sEVs secreted from lung cancer tissue contained EGFR." (PMID 34094979, 2021). "Although phenotype characteristics of EGFR-TKI-resistant lung cancer cells can be classified as EGFR-dependent and EGFR-independent growth, deciding an appropriate treatment strategy is difficult due to the acquired resistance being driven by heterogeneous mechanisms." (PMID 34367462, 2021). "Besides, other factors activated by EGFR such as the EGFR downstream STAT3 has also been demonstrated contributing to radioresistance as a therapeutic target reverses radioresistance in lung cancer." (PMID 34685495, 2021). "In addition to observations in lung cancer, EGFR has also been found to activate the MAPK/Akt/STAT/Myc signaling pathways to upregulate PD-L1 expression in head and neck, esophageal, gastric, salivary adenoid cystic carcinoma and EGFR-positive cancers." (PMID 34503236, 2021). "EGFR-TKI resistance promotes immune escape in lung cancer via up-regulating PD-L1 expression." (PMID 33777742, 2021). "The EGF-receptor (EGFR) has become an important target in clinical oncology, and EGFR-targeting kinase inhibitors and monoclonal antibodies are routinely used in the treatment of lung cancer, head and neck cancer, and colorectal cancer." (PMID 33777943, 2021). "In lung cancer, the analyzed SNPs were previously investigated mainly in the context of response to targeted treatment with EGFR TKIs or, in colorectal and head and neck cancer, to treatment with anti-EGFR mAbs such as cetuximab." (PMID 34070597, 2021). "Moreover, high dose weekly erlotinib, in the range of 1000 mg – 1500 mg, effectively controls CNS metastases in EGFR mutant lung cancer patients." (PMID 33993094, 2021). "These ASR trends of EGFR mutation-negative lung cancer corresponded to the proportions of ever-smokers in those ethnic subgroups, except for Pacifica versus New Zealand Europeans." (PMID 33961689, 2021). "Therefore, the core compounds identified in this study can be used as potential therapeutic drugs for lung cancer, and their anti-inflammatory activities can provide a pharmacological reference for alleviating the adverse reaction of diarrhea to EGFR-TKI." (PMID 33868436, 2021). "Thus, as our study is exploratory in nature, additional research is necessary to elucidate the role of EGFR SNPs in modulating the sensitivity to RT and platinum drugs and lung cancer prognosis." (PMID 34070597, 2021). "In addition, it is important to mention that alterations in EGF signalling pathway have been observed in several pathologies being lung cancer a paradoxical example of EGFR targeted therapy." (PMID 34655447, 2021). "EGFR-KDD has mostly been studied in lung cancer with regard to clinical outcomes." (PMID 34867402, 2021). "The single nucleotide polymorphisms of ESR2 are closely related to lung cancer in nonsmoking women, and studies have shown that nonsmoking women in Asia have a higher mutation rate of the EGFR gene." (PMID 33868436, 2021). "Indeed, integrins have been reported to control the EGFR signaling pathway and induce EGFR clustering, so we believe that CD151 regulates EGFR signaling pathway by controlling integrins in lung cancer." (PMID 34108040, 2021). "This therapy could be applied in oncologic surgical interventions in EGFR-expressing tumors, such as head-and-neck cancer, bladder cancer, lung cancer and brain tumors." (PMID 33498707, 2021).
lung cancer (continued). "We confirmed meaningful insight that CME could contribute to treating lung cancer, but some limitations remain for EGFR endocytosis studies." (PMID 33314735, 2021). "Therefore, we propose that targeting cell cycle processes or protein ubiquitination pathways are promising treatment strategies for overcoming resistance to EGFR inhibitors in lung cancer." (PMID 33188726, 2021). "Lung cancer treatments have been refined greatly, with constantly and novelly emerging components, and the small molecular compounds improved the life quality and expected response to therapies in patients carrying sensitive EGFR mutants." (PMID 34656164, 2021). "Furthermore, ROR1 has been identified as a transcriptional target of homeobox protein NKX-2, which is required for sustained EGFR signaling in lung cancer patients and serves as an independent prognostic predictor of OS." (PMID 34319035, 2021). "As a consequence, further exploration of ID1 in EGFR T790M-positive lung cancer cells is required." (PMID 33992097, 2021). "Moreover, in lung cancer patients, there is a positive correlation between EGFR and PD-L1 expression." (PMID 34211836, 2021). "Besides, patients with ALK-positive lung cancers were significantly younger and were found at higher clinical stage at diagnosis compared with EGFR mutant cohorts." (PMID 34234236, 2021). "Of note, Erlotinib is highly effective in inhibiting EGFR with kinase domain mutations that are prevalent in lung cancer as opposed to its low efficacy in blocking EGFR with extracellular domain mutations that are characteristic of GBM." (PMID 33673213, 2021). "Importantly, EGFR signaling activation has been recently shown to be an important escape mechanism upon KRAS inhibition or gemcitabine treatment in lung cancer and PDAC cancer, respectively." (PMID 33670598, 2021). "Furthermore, treatment combining EGFR inhibitors and sorafenib has been considered, showing promising results in lung cancer." (PMID 34655447, 2021). "This phenomenon is similar to that in the western medicine that certain drugs, such as antifungal drugs, could induce primary and acquired resistance of EGFR-TKI in lung cancer." (PMID 34646330, 2021). "EGFR and KRAS mutations are the most frequently found mutations in lung cancer." (PMID 34439281, 2021). "Similarly, loss of H3K9 methylation at the BCAT1 gene promoter coincides with increased BCAT1 expression in tyrosine kinase inhibitor (TKI)-resistant epidermal growth factor receptor (EGFR)-mutant lung cancer cells." (PMID 34109280, 2021). "For example, in EGFR-mutant lung cancer, HGF may be involved in endogenous and acquired resistance to acid kinase inhibitors." (PMID 34745947, 2021). "It has previously been demonstrated that EGFR mutation is highly prevalent in lung cancer patients who were never smokers." (PMID 33300283, 2021). "The development of EGFR tyrosine kinase inhibitors (EGFR-TKIs) represents considerable progress for the treatment of lung cancer, and they are now recognized first-line treatments for NSCLC patients who have activating EGFR mutations (within exon 19 and the L858R missense mutation within exon 21)." (PMID 33855679, 2021). "Silencing alters sensitivity to anticancer drugs targeted to c-Met/EGFR in lung cancer cells." (PMID 34026616, 2021). "In the subgroup analyses, underweight lung cancer patients were older in those with wild type EGFR." (PMID 34836017, 2021). "Previous studies have shown that ACE2 attenuated the metastasis of lung cancer and that TMPRSS2 fusion gene may induce resistance to EGFR-TKI, a standard first-line therapy for advanced NSCLC patients harboring EGFR mutation." (PMID 34094930, 2021). "Though molecular targeted therapies, especially epidermal growth factor receptor (EGFR)-tyrosine kinase inhibitors (TKIs), have largely improved the survival of oncogene-driven lung cancer patients, few studies have focused on the performance of TKI in such settings." (PMID 34680533, 2021).
lung cancer (continued). "Small cell transformation of non‐small cell lung cancer (NSCLC) is commonly recognized as one of the resistance mechanisms to epidermal growth factor receptor (EGFR)‐tyrosine kinase inhibitors (TKIs) in EGFR‐mutant NSCLC treatment, which accounts for 3%–14% of resistant cases." (PMID 34622569, 2021). "However, the distribution and prevalence of epidermal growth factor receptor (EGFR) germline variants and their roles in lung cancer genetic predisposition in Chinese population remain to be elucidated." (PMID 34869019, 2021). "Over the past few years, the introduction of the epidermal growth factor receptor (EGFR), tyrosine kinase inhibitors (TKIs), and anaplastic lymphoma kinase (ALK)-based target therapy dramatically improved the therapeutic efficacy for lung cancer patients with specific gene mutations." (PMID 34307450, 2021). "Moreover, treatment of lung cancer cells with TKIs targeting MET (proto-oncogene) or EGFR gene alterations can instruct the TME to sustain an adaptive resistance to targeted therapies by increasing lactate release." (PMID 33673405, 2021). "However, identification of the major driver mutations in lung cancer patients such as KRAS and EGFR mutations along with expression of PD-L1 would greatly help designing combination treatments for better response." (PMID 33956842, 2021). "miR-7-5p suppresses the growth of lung cancer cells through others EGFR pathway." (PMID 33422052, 2021). "In our study, the observation period for postoperative recurrence of EGFR mutation-positive lung cancer is not consistent." (PMID 34298845, 2021). "Somatic alterations of EGFR are found in many lung cancer cases." (PMID 34359977, 2021). "Identifying impactful ways to broaden this TKI-stimulated transcriptional program in lung tumors may provide a path to more durable clinical response in EGFR mutant lung cancers." (PMID 34001994, 2021). "In the period 2013–2017, EGFR mutation testing in the Netherlands has transformed from a single-gene approach to the nationwide implementation of NGS using a multigene panel for predictive biomarker testing including EGFR according to the current Dutch national guideline for lung cancer." (PMID 34298851, 2021). "To date, ICB therapy in EGFR mutant lung cancer has been disappointing." (PMID 35008514, 2021). "This in silico study suggests that Wi-A, Wi-N and CAPE may be recruited for the treatment of aberrant EGFR driven lung cancers." (PMID 33530424, 2021). "Because the de novo prevalence of MET amplification and overlap by verifying degrees with other oncogenic drivers are confounding factors that need to be studied in greater detail, our MET ISH results for EGFR-TKI-resistant lung cancer have clinical relevance in routine practice." (PMID 34205733, 2021). "METTL3, as an RNA methyltransferase, promotes the translation of certain mRNAs, incorporating the Hippo pathway effector TAZ and epidermal growth factor receptor (EGFR) among human cancer cells, which promotes growth, invasion, and survival in human lung cancer cells." (PMID 34150845, 2021). "Importantly, A2BR blockage also suppressed EGFR translocation and its phosphorylation upon γ-irradiation, thwarting EGFR-mediated recovery of lung cancer cells from γ-radiation-stimulated DNA damage." (PMID 34830449, 2021). "As miR-214 may confer gefitinib resistance in lung cancer cells, downregulating miR-214 could counter EGFR-TKI resistance." (PMID 34943783, 2021). "Notably, the JUNIPER trial in KRASMUT lung cancer has showed that the CDK4/6i Abemaciclib performed better than the EGFR inhibitor Erlotinib, in term of both objective responses and progression free survival (NCT02152631)." (PMID 34654798, 2021). "Whether programmed death-ligand 1 (PD-L1) expression could predict the outcome of tyrosine kinase inhibitor (TKI) treatment and prognosis of epidermal growth factor receptor (EGFR)-mutant nonsmall cell lung cancer (NSCLC) is remaining controversial." (PMID 34449486, 2021).
lung cancer (continued). "Our studies provided rationale to target MUC3A combining with TKIs in EGFR-mutant lung cancers." (PMID 33994852, 2021). "The nicotine signaling in lung cancer cells can also be enhanced by mitogenic receptor tyrosine kinases (RTKs) activation due to formation of heterocomplexes between α7-nAChRs and some RTKs, such as epidermal growth factor receptor (EGFR)." (PMID 34595181, 2021). "Moreover, higher PD-L1 expression was observed in mutant EGFR and K-ras lung cancer cells through an Akt/mTOR-dependent mechanism." (PMID 34503236, 2021). "It is however debated if copy number gain may act as a predictive marker for EGFR-TKI response in patients with EGFR wild type lung cancer tumors." (PMID 34625038, 2021). "Based on TMB and ITH, survival analyses were performed to identify their predictive and prognostic value for first-line chemotherapy in lung cancer patients without EGFR/ALK mutations." (PMID 34604048, 2021). "We then used the prediction of epidermal growth factor receptor (EGFR) status in lung cancer as an example, because lung cancer diagnosis and treatment are important topics of research, since various tumor characteristics have diagnostic and prognostic factors." (PMID 34941646, 2021). "Therefore, increased endothelial EGFR expression is accompanied by pleural angiogenesis in lung cancer." (PMID 34680445, 2021). "Lung cancer cells have been shown to express and secrete EGFR through MVs." (PMID 34830787, 2021). "In lung cancer, evidence of prognostic and predictive value is available for monitoring of the human epidermal growth factor receptor T790M (EGFR T790M) resistance to EGFR tyrosine kinase inhibitors (EGFR-TKI), as reflected by the FDA approval for the Cobas EGFR mutation test in 2016." (PMID 33440749, 2021). "Different publications have found an association between female sex and better prognosis in lung cancer independent of EGFR mutation status." (PMID 34465283, 2021). "As KRT19 correlated with EGFR wt lung cancer, KRT19 may be a valuable predictive marker for EGFR-TKI use." (PMID 33442422, 2021). "Studies suggested that persistent differences in lung cancer incidence among different ethnic populations were not entirely explained by variations in smoking history, for which, EGFR mutation-positive lung cancer exemplifies." (PMID 33961689, 2021). "Unexpectedly, the initial trials of EGFR TKIs identified higher ORR and improved outcomes among young women, non-smokers, and Asians with lung cancer, reflecting the fact that the frequency of EGFR mutations is higher in these patient groups." (PMID 34202748, 2021). "Germline p.T790M and p.V843I in epidermal growth factor receptor (EGFR) and parkin RBR E3 ubiquitin protein ligase (PARK2) loss-of-function mutations have been identified in these families and suggested to confer the high susceptibility to lung cancer." (PMID 33898318, 2021). "EGFR expression in cancer cells can help define therapy strategies of lung cancer patients." (PMID 34083661, 2021). "EGFR T790M is the most frequent mutation in Western countries, with a 0.54% frequency in nonsmokers and 0.34% in patients with nonsquamous nonsmall cell lung cancer (NSCLC)." (PMID 34869019, 2021). "Besides, the synergistic pretreatment with miR-125a-5p augmented the cytotoxic effect of erlotinib by reducing cellular proliferation, and enhanced the apoptotic effect, thus bypassing the resistance to EGFR-TKIs in lung cancer cells." (PMID 34830377, 2021). "The results in the present study independently predicted that HDACis may be potential drugs for patients with high-RS EGFR-WT NSCLC and implicated the possibility of HDACis as single drugs for lung cancer therapy." (PMID 33763356, 2021).